KLHDC8B (kelch domain containing 8B)
Description:
Involved in pinching off the separated nuclei at the cleavage furrow and in cytokinesis. Required for mitotic integrity and maintenance of chromosomal stability. Protects cells against mitotic errors, centrosomal amplification, micronucleus formation and aneuploidy. Plays a key role of midbody function involving abscission of the daughter cells during cytokinesis and appropriate chromosomal and nuclear segregation into the daughter cells.
Synonyms: MGC35097; CHL
Tractability: PROTAC: ubiquitination databases record sites on it; its protein half-life has been measured.
Gene: Protein-coding gene on chromosome 3 (49,171,239 to 49,176,487, forward strand). Ensembl gene ENSG00000185909.
Subcellular location: Cytoplasm; Midbody
Subcellular location (Human Protein Atlas): Cytosol
Gene Ontology:
Biological process: mitotic cytokinetic process; mitotic nuclear division; nuclear chromosome segregation
Cellular component: cellularization cleavage furrow; cytoplasm; cytosol; intercellular bridge; midbody
Genetic constraint (gnomAD): Loss-of-function variants: 19 observed, 27.45 expected, observed/expected ratio (o/e) 0.69, 90% interval 0.48 to 1.02. The synonymous counts are far from expectation, so gnomAD's model fits this gene poorly and the ratio says little. Missense variants: 411 observed, 500.13 expected, observed/expected ratio (o/e) 0.82, 90% interval 0.76 to 0.89. Synonymous variants: 150 observed, 195.65 expected, observed/expected ratio (o/e) 0.77, 90% interval 0.67 to 0.88.
Homologues: Orthologues: chimpanzee KLHDC8B (99% identical), macaque KLHDC8B (99% identical), rabbit KLHDC8B (98% identical), mouse Klhdc8b (98% identical), rat Klhdc8b (97% identical), dog KLHDC8B (97% identical), guinea pig KLHDC8B (95% identical), pig KLHDC8B (95% identical), tropical clawed frog klhdc8b (68% identical). Paralogues in human: KLHDC8A (45% identical), KLHL28 (26% identical), KLHL12 (26% identical), KEAP1 (25% identical), KLHL18 (25% identical), KLHL5 (25% identical), KLHL3 (24% identical), KLHL1 (24% identical), KLHL20 (24% identical), KLHL8 (24% identical), KLHL29 (24% identical), IPP (23% identical), and 42 more.
Diseases named in the same sentence as KLHDC8B in open-access papers:
KLHDC8B is named in the same sentence as 8 diseases in open-access papers, as found by Europe PMC text mining. Sharing a sentence is not in itself a finding about the gene and the disease. The quoted sentences say what the papers report.
Hodgkins lymphoma (3 papers, 2013 to 2022). A heterogeneous group of malignant lymphoid neoplasms of B-cell origin characterized histologically by the presence of Hodgkin and Reed-Sternberg (HRS) cells in the vast majority of cases. "Meat quality index was negatively correlated with expression of the third exon of KLHDC8B and this gene is associated with some cases of classical Hodgkin lymphoma which is characterized by binucleated cells." (PMID 33175867, 2020). "Multiple cases of Hodgkin's lymphoma with translocations or polymorphisms affecting KLHDC8B have been reported in the same family, indicating that inhibition of its expression plays a role in B cell transformation." (PMID 23516355, 2013).
depression (1 paper, 2022). "We identified just two genes that met all three criteria: KLHDC8B and TMEM161B-AS1, with increased expression in depression, regulated respectively by two GWAS-confirmed risk alleles, rs7617480 and rs3099439." (PMID 36171190, 2022).
metastatic cancers (1 paper, 2021). A carcinoma which has spread from the original site of growth to another anatomic site. "FCGR2A and KLHDC8B in TEPs were positively related to metastatic cancers in comparison with healthy controls and had potential diagnostic significance for metastatic cancers with a sensitivity of 61.8%, 59.7%, and a specificity of 89.1%, 83.6%, respectively." (PMID 33955587, 2021). "Moreover, ARL2, FCGR2A, and KLHDC8B were positively associated with advanced, metastatic cancers compared to healthy controls." (PMID 33955587, 2021).
cancer (2 papers, 2015 to 2021). A tumor composed of atypical neoplastic, often pleomorphic cells that invade other tissues. "After exposure to VPA, we observed changes in the expression levels of several genes (TPT1, ARAP3, and KLHDC8B) that are reported to be important in cancer-related pathways." (PMID 26379622, 2015). "Seven TEPs mRNAs were discovered in our study: RSL24D1, IFI27, CRYM, HBD, IFITM3, FCGR2A, and KLHDC8B in TEPs, which are mainly enriched in protein binding, extracellular matrix, and metabolic process, and may be used for cancer diagnosis." (PMID 33955587, 2021). "Consequently, we believe alternative TEPs mRNAs, including RSL24D1, IFI27, CRYM, HBD, IFITM3, FCGR2A, and KLHDC8B mRNA, can potentially serve as non‐invasive biomarkers for diagnosing cancers and can even predict the prognosis of pan‐cancer." (PMID 33955587, 2021). "In this study, 7 TEPs mRNAs were verified, including RSL24D1, IFI27, CRYM, HBD, IFITM3, FCGR2A, and KLHDC8B, which may be used for cancer detection." (PMID 33955587, 2021).
KLHDC8B also shares sentences with these, for which no sentence is quoted: bladder cancer (1 paper); DICER1 syndrome (1); metastatic tumor (1); tumor (1).